DNMT1 (DNA methyltransferase 1)
Diseases named in the same sentence as DNMT1 in open-access papers (continued):
Sharing a sentence is not in itself a finding about the gene and the disease.
tumor (continued). "Genetic disruption of both DNMT1 and DNMT3B resulted in greater than 95% reduction in genomic cytosine-5 DNA methylation and re-activation of silenced tumor suppressor genes." (PMID 21629434, 2010). "DNMT1, DNMT3A and DNMT3B were substantially over-expressed in human hepatocarcinogenesis accompanied by a marked increase of tumor suppressor genes methylation." (PMID 21629434, 2010). "Compared with inhibition of DNMT1, DNMT3B siRNA induced more tumor-related genes identical to that of demehylation drug 5-aza-2’-deoxycytidine." (PMID 27994704, 2008). "In this study, we measured the mRNA expression level of three methylation-related genes (DNMT1, DNMT3b and MBD2) in NSCLC tumour tissues using quantitative real-time PCR and evaluated their prognostic values." (PMID 18414412, 2008). "Mechanistically, DNMT1‐mediated suppression of CBX7 activates the extracellular signal‐regulated kinase (ERK) pathway through increased ERK phosphorylation, thereby facilitating tumor growth and progression." (PMID 40387566, 2025). "One of the 7 patients (14%) with analyzable paired tumor biopsy specimens exhibited an appreciable increase in tumor p16 expression, and none had appreciable decreases in qualitative tumor DNMT1 levels." (PMID 41428220, 2025). "Therefore, miR‐185 plays a role in inhibiting tumour growth during the development of TNBC, suggesting the miR‐185/DNMT1 axis is a promising therapeutic approach for TNBC." (PMID 40387409, 2025). "Studies have shown that overexpression of DNMT1 leads to methylation-mediated silencing of promoter regions of multiple tumor suppressor genes (such as p16, RASSF1A, and CDH1), thereby inhibiting apoptosis and promoting tumor cell proliferation and invasion." (PMID 41394878, 2025). "They additionally revealed that an increased expression of DNMT1 could counteract the impact of miR‐152‐3p upregulation on the progression of CRC and the growth of tumours." (PMID 40387409, 2025). "After the test, it was found that DNMT1 and HDAC1/2 in the tumor tissue were significantly downregulated, while the transcriptional levels of pro-apoptotic genes such as BAX, BNIP3, and APAF1 were significantly increased, and the tumor volume was significantly reduced." (PMID 41335282, 2025). "In view of the structural similarities between DNMT1, and KMT2A we investigated if DEC is able to not only degrade DNMT1 but also KMT2A, possibly revealing a previously unknown DEC‐induced anti‐tumor mechanism." (PMID 39754404, 2025). "Moreover, in vivo findings demonstrated that PPI triggers inhibition of tumour growth, HOTAIR and the protein expressions of DNMT1 and EZH2." (PMID 40387409, 2025). "Therefore, AKT/RICTOR-mediated phosphorylation of DNMT1 and/or KDM5A regulates gene expression, including that of UGCG, leading to an increase in glucosylceramides and enhanced tumor progression." (PMID 40934285, 2025). "This expanded context makes clear that our observation of miR-152-3p downregulation is well-supported by the literature and may have functional consequences (de-repression of miR-152 targets like DNMT1 or FOXR2, which promote tumor aggressiveness)." (PMID 41462933, 2025). "The study indicated that, in tumor samples from patients with recurrence, the NNMT expression was elevated while the DNMT1 expression was reduced, resulting in tumor cell resistance to oxidative phosphorylation inhibitors, thus rendering these treatments ineffective and promoting tumor relapse." (PMID 40427612, 2025). "Conversely, DNMT1-mediated methylation silences chemokines such as CXCL9 and CXCL10, leading to reduced anti-tumor immune cell infiltration; the restoration of TET1 and TET2 can reverse this effect and improve the efficacy of immune checkpoint inhibitors (ICIs)." (PMID 41394878, 2025). "They observed that the downregulation of DNMT1 or the upregulation of miR‐152‐3p resulted in a decrease in TMSB10 expression, thereby exerting inhibitory effects on the progression of CRC and the growth of tumours." (PMID 40387409, 2025).
tumor (continued). "Therapeutically, by antagonizing miR-142-3p, or pharmacologically, by suppressing DNMT1, could restore CDH13 expression and inhibit tumor progression." (PMID 40649905, 2025). "The reduced DNMT1 protein levels, increased unmethylated promoter amounts, increased miR‐302a‐3p levels, and reduced ATP7B mRNA levels in PLB‐treated tumor samples further support that the DNMT1/miR‐302a‐3p/ATP7B axis mediated cuproptosis triggered by PLB in vivo." (PMID 40761482, 2025). "We hypothesized that the double targeting of G9a/DNMT1 in human and murine NSCLC models would have a strong impact on tumor growth in combination with other therapies, as a result of CM-272-mediated gene expression reprogramming leading to chemosensitization." (PMID 39488528, 2024). "Compared to the ICA + CUR group, the ICA + CUR + SCFAs group showed a significant increase expression of IGFBP2 in the liver and tumor tissues, while DNMT1 expression showed no significant change." (PMID 38778379, 2024). "Additionally, downregulation of DNA (cytosine-5)-methyltransferase 1 (DNMT1), which is involved in the hypermethylation of various tumor-suppressor genes, and poor prognosis in GBM were reported." (PMID 38672652, 2024). "We revealed the relationship between TET2 upregulation, demethylation and tumor suppressor re-expression, and concomitant resistance to DNMTi in the absence of the DNMT1 gene." (PMID 39057134, 2024). "Furthermore, our data indicate that continuous combination therapy of DNMT1 and SMO inhibitors acts synergistically to inhibit tumor growth." (PMID 39107797, 2024). "Therefore, the aim of this study was to identify DNA sequence variation in DNMT1 rs2228611, rs2228612 and DNMT3A rs2276598, rs752208, as well as to investigate their effect on the tumor phenotype and disease prognosis in BC patients." (PMID 39597087, 2024). "Specifically, the study aimed to assess how DNMT1 and DNMT3A, influenced by EZH2, affect the methylation and expression levels of miR-570-3p, and to determine the impact of estradiol (E2) on these processes and the subsequent effects on PTC tumor growth." (PMID 38890707, 2024). "Third, inhibition of DNMT1 blocked SHH pathway output as supported by a previous study, and pathway inhibition as well as anti-tumor activity were also seen in the presence of genetic alterations within the SHH pathway previously shown to render tumors resistant to SMO inhibition." (PMID 39107797, 2024). "Combination treatment in vitro was significantly more effective in inhibiting tumor growth and SHH activation than either SMO and DNMT1 inhibitors alone, and this synergistic effect was seen in both murine and human cell models of SHH-MB sensitive to SMO inhibitors." (PMID 39107797, 2024). "We revealed the relationship between TET2 upregulation, demethylation, and tumor suppressor re-expression, and concomitant resistance to DNMTi in the absence of DNMT1." (PMID 39057134, 2024). "Compared to the FMT-PCa group, the FMT-PCa-ICA + CUR group experienced a reduction in the expression of IGFBP2 in the tumor tissues, with no significant change in DNMT1." (PMID 38778379, 2024). "Furthermore, simultaneous inhibition of both DNMT1 and SMO acts synergistically to inhibit tumor growth in in vitro and in vivo models of SHH-MB." (PMID 39107797, 2024). "For example, EZH2-mediated H3K27me3 and DNMT1-mediated DNA methylation in ovarian cancer reduce the levels of the chemokines CXCL9 and CXCL10 secreted by helper T cells (Th1), increasing CD8+ T cell infiltration, and inhibiting tumor growth." (PMID 38988323, 2024). "Furthermore, our research elucidated the tumor-promoting function of PI3K-AKT and CDK2-Rb activation, both of which can be suppressed by DNMT1-specific DNA hypomethylation." (PMID 38755637, 2024). "In conclusion, it was the DNA damage effects in the presence of DNMT1 without re-expression of tumor suppressors that were responsible for the anticancer activity of prototypical and novel DNMT inhibitors." (PMID 37045940, 2023).
tumor (continued). "In summary, we discovered that mTOR regulates DNMT1 in a 4E-BP1-dependent manner to affect DNA methylation profiles, which emphasizes that dysregulation of oncogenic pathways can alter the epigenetic status to affect tumour growth." (PMID 37088830, 2023). "Namely, we hypothesize that DNMT1 and DNTM3A seem to play a role in tumor initiation, DNMT3B in tumor progression and DNMT3L in tumor relapse, whereas DNMT2 may have an opposite role." (PMID 37894317, 2023). "Additionally, we discovered that the levels of three DNA methyltransferases (DNMT1, DNMT3A, and DNMT3B) were significantly higher in the CBX2high tumor than the CBX2low tumor and the CEP55high tumor than the CEP55low tumor." (PMID 37980163, 2023). "Taken together, these data suggest that FGF2, through both DNMT1/ERK-dependent and -independent pathways, potently antagonizes the expression of EC CAMs and chemokines that are important for CTL homing and entry into tumors or tumor-draining lymph nodes." (PMID 37055433, 2023). "Interestingly, a recent IHC study also analyzed the protein expression of DNMT1 and DNMT3A in relation to tumor stage." (PMID 37367043, 2023). "Targeting Dnmt1 in ECs reduces proliferation but augments Th1 chemokine production and extravasation of CD8+ T-cells, suggesting DNMT1 programs immunologically anergic tumor vasculature." (PMID 37055433, 2023). "In this study, the expression of DNMT1 significantly increased in After Tumor, whereas the expression of DNMT3A and DNMT3B did not change." (PMID 38136558, 2023). "The results revealed significant elevation of NSUN7 and DNMT1 in normal tissues compared with tumor tissues, while NSUN4 showed no obvious difference between the two groups." (PMID 36911744, 2023). "Overall, our study suggests that DNMT1, 3A, and 3B are not biological determinants of CpG73 hypermethylation in tumor cells." (PMID 37367043, 2023). "Combined inhibition of EZH2 and DNMT1 augmented the expression of the inflammatory chemokines CXCL9 and CXCL10, which increased TILs and decreased tumor progression, thus improving the therapeutic efficacy of PD-L1 checkpoint blockade and adoptive T-cell transfusion in tumor-bearing mice." (PMID 37198402, 2023). "For example, DNMT1, DNMT3A, and DNMT3B have been shown to promote LAML, which may be due to DNMTs silencing certain tumor suppressor genes through hypermethylation of these genes, thereby promoting the progression of LAML." (PMID 37308972, 2023). "Here, analysis of the correlation between CARM1 and four methyltransferases (DNMT1, DNMT2, DNMT3a, DNMT3b) expression was conducted for each tumor to explore whether CARM1 expression is related to epigenetics." (PMID 35033016, 2022). "Immunohistochemistry analysis showed that the expression of WTAP, DNMT1, and DNMT3B in tumor tissues was significantly higher than that in paracancerous tissues, whereas the expression of TRMT6 was low in tumor tissues." (PMID 36203569, 2022). "Inhibition of DNMT1 and, or BCAT1 activity may inhibit tumor development by blocking this proliferative pathway." (PMID 36119495, 2022). "Further, EZH2 in combination with DNMT1 had a negative correlation with CD8+ T cells tumor infiltration and prognosis of OC patients." (PMID 36545327, 2022). "In addition, zeste homolog 2 (EZH2)-mediated histone lysine methylation and DNA methyltransferase-1 (DNMT-1)-mediated DNA methylation suppressed the production of CXCL9 and CXCL10 respectively, and then inhibited T-cell tumor homing." (PMID 35493527, 2022). "It has been reported that the DNA methylation mediated by DNMT1 and EZH2 silences a lot of genes including miR-200b/a/429 expression and promotes tumor progression, which may help explain why EZH2 depletion has different effects from EZH2 inhibitors sometimes." (PMID 36038549, 2022).
tumor (continued). "A study found that EZH2-mediated H3K27me3 along with DNMT1-mediated DNA methylation inhibited generation of Th1 chemokines, including CXCL9 and CXCL10, which helped effector T cells migrate to microenvironment in tumor." (PMID 36545327, 2022). "Selective nonnucleoside DNMT1 inhibitors in the DC_05 series of compounds can also play an anticancer role by inducing DNA hypomethylation to restore tumor suppressor gene expression." (PMID 34452630, 2021). "DNMT1 forms complexes with UHRF1 and HDAC1 proteins in tumor cells, reducing expression of tumor suppressor promoter genes (e.g., P16INK4A, P14ARF, and P21) and hence fostering tumor growth." (PMID 33941774, 2021). "Consistent with our results, we found that DNMT1 expression was increased in tumour tissues compared with normal tissues in the TMA and TCGA cohort." (PMID 34589490, 2021). "We found NDRG1 expression was significantly inverse correlated with invasion depth (p = 0.023), whereas DNMT1 was statistically significantly positive correlated with invasion depth (p = 0.049), DNMT3B was significantly positive correlated with the degree of tumor cell differentiation (p = 0.030)." (PMID 34616614, 2021). "Susanna F. Greer found that downregulation of DNMT1 and HDAC1 expression in ovarian cancer cells induced by overexpression of RGS10 could inhibit tumor drug resistance." (PMID 34073721, 2021). "IHC was carried out to detect DNMT1, TRAF1, p65, VEGF and CD34 in tumor tissues." (PMID 34749775, 2021). "Hypermethylation of the CpG islands around promoters of specific suppressor genes, predominantly maintained by the DNA methyltransferase 1 (DNMT1), can be stably inherited for multiple generations in tumor cells and is involved in the process of carcinogenesis and progression of CRC." (PMID 34922605, 2021). "In the epigenetic regulation, E7 could upregulate DNA methyltransferases DNMT1, DNMT3A, and DNMT3B to promote genomic instability 17, induce methylation of CXCL14 to promote tumor growth via angiogenesis." (PMID 34729114, 2021). "Indeed, experimental evidence suggests that DNMT1 and DNMT3B are responsible for p16 promoter hyper-methylation, this leading to its inactivation in several tumours." (PMID 34831178, 2021). "In addition to its NAT activities, acetyltransferase-independent NAA10 interaction with DNA methyltransferase 1 (DNMT1) facilitates DNA methylation and the maintenance of genomic imprinting as well as tumor suppressor silencing." (PMID 34769235, 2021). "According to a study, both mir-148b and mir-152 can reactivate some tumor suppressor genes such as SPARC and BNIP3 by targeting DNMT-1, thereby resulting in modification of methylation status of the mentioned tumor suppressor genes and reducing tumorigenic properties in pancreatic cancer cell lines." (PMID 33632341, 2021). "Moreover, LAN‐mediated circadian rhythm disorder downregulated the expression of Ces1 and Sirt1, upregulated the expression of Dnmt1, while MLT supplementation eliminated the effects in the mouse tumor tissues." (PMID 34185414, 2021). "In contrast, DNMT1 expression in tumor tissues was not significantly different from that in normal adjacent tissues." (PMID 34946098, 2021).
tumor (continued). "Our current study demonstrated that the mRNA levels in cells and the protein levels in the supernatants of DNMT1, DNMT3a, DNMT3b, and HDAC1 increased with the increase of cell malignancy, which has provided a critical evidence in the search for tumor biomarkers from body fluid." (PMID 33383878, 2020). "We next measured the levels of DNMT1, DNMT3A and DNMT3B in these tumor tissues." (PMID 30948928, 2019). "In contrast, some results indicated that DNMT1 was neither overexpressed in PTC nor correlated with tumor stage and capsular/vascular or lymphatic invasion." (PMID 31754358, 2019). "Inhibitors of epigenetic modulators such as DNA methyltransferase 1 (DNMT1), histone deacetylases (HDACs) and bromodomain and extra-terminal (BET) inhibitors have shown capabilities to function as differentiation therapies for CSCs in various tumor types." (PMID 30834247, 2019). "EZH2-mediated H3K27me3 and DNMT1-mediated DNA methylation repress the tumor production of T helper 1 (Th1)-type chemokines CXCL9 and CXCL10, and subsequently determine effector T-cell trafficking to the tumor microenvironment." (PMID 29556394, 2018). "Next, we selected several EZH2, LSD1 or DNMT1 potential targets (P15, P21, LATS2, RND1, KLF2, NKD2, PTEN) with tumor-suppressor function and SPRY4, and hypothesized that they may involve in the contributions of SPRY4-IT1 to CCA progression." (PMID 29642935, 2018). "Indeed, a specific peptide-mediated disruption of DNMT1/PCNA, DNMT1/HDAC1, DNMT1/DNMT3B, or DNMT1/HP1 interactions promoted global DNA hypomethylation in astrocytes and increased tumor growth." (PMID 29449903, 2018). "There was ≥ 1.5-fold change in expression of DNMT1 in GBM50 and GBM0.2 tumours, suggesting that the reduction in mtDNA copy number strongly induced DNA demethylation in the tumours, and is probably the major reason why the majority of regions were hypo-methylated." (PMID 30208958, 2018). "VEGFA induced DNMT3A, but not related DNMT3B or DNMT1, and DNMT3A knockdown prevented VEGFA‐mediated miR‐128 loss and the increases in Bmi1 expression and OVCA tumor sphere formation in vitro." (PMID 28179359, 2017). "By Western blot, fresh tumours harvested from the experiment showed that solamargine significantly decreased EP4, DNMT1 and c‐Jun protein expression and induced phosphorylation of ERK1/2 in vivo in the high‐dose solamargine treatment group compared with the control group." (PMID 27620163, 2017). "We then investigated whether NT1721 influenced the expression of tumor suppressor genes since several reports have shown links between the downregulation of DNMT1, BMI1 and EZH2 and increased expression of tumor suppressor genes." (PMID 27863389, 2016). "Additionally, our study provides a rationale for therapies administered in combination with 5-Aza-Cd to effectively reprogram the transcription of silenced genes in tumor cells based on assessments of the expression levels of EHMT2 and DNMT1." (PMID 27174920, 2016). "While we did not observe any consistent changes in the levels of Dnmt1 in either tumor type, we did see down regulation of Dnmt3b in PTCL, but not CLL samples, relative to their respective controls." (PMID 27677595, 2016). "We believed that our findings provided the novel insight into the connection between SAPK/JNK signaling and expression of DNMT1 and EZH2 affected by PPI, and also highlighted the tumor suppressor role of SAPK/JNK that was involved in the anti-tumor effects of PPI." (PMID 27421653, 2016). "The expression of DNMT1 was mostly negative in the tumor stroma, compatible with previous results showing no or low immunohistochemical reaction to DNMT1 in the tumor stroma and normal stroma." (PMID 27071379, 2016). "To investigate the factors involved in TSG hypermethylation in NSCLC, we attempted to determine whether DNMT1 and DNMT3B RNA expression levels correlated with the hypermethylation of the promoters of the studied tumor suppressor genes." (PMID 26112163, 2015).